TTLL11 (tubulin tyrosine ligase like 11)
Description:
Polyglutamylase which modifies tubulin, generating polyglutamate side chains of variable lengths on the gamma-carboxyl group of specific glutamate residues within the C-terminal tail of tubulin. Preferentially mediates ATP-dependent polyglutamate long side-chain elongation over the initiation step of the polyglutamylation reaction. Preferentially modifies the alpha-tubulin tail over a beta-tail (By similarity). Required for CCSAP localization to both spindle and cilia microtubules. Promotes tubulin polyglutamylation which stimulates spastin/SPAST-mediated microtubule severing, thereby regulating microtubule functions (By similarity).
Synonyms: C9orf20; bA244O19.1; C9orf148; TTLL11-IT1
Tractability: No criterion of Open Targets' tractability assessment is met for any kind of drug.
Gene: Protein-coding gene on chromosome 9 (121,815,674 to 122,093,606, reverse strand). Ensembl gene ENSG00000175764.
Subcellular location: Cytoplasm, cytoskeleton, cilium basal body; Cytoplasm, cytoskeleton
Pathways (Reactome):
Metabolism of proteins: Carboxyterminal post-translational modifications of tubulin
Gene Ontology:
Molecular function: protein-glutamic acid ligase activity, elongating; protein-glutamic acid ligase activity, initiating; tubulin binding; tubulin-glutamic acid ligase activity
Biological process: microtubule cytoskeleton organization; protein polyglutamylation
Cellular component: ciliary basal body; cytosol; cytoskeleton
Genetic constraint (gnomAD): Loss-of-function variants: 32 observed, 41.18 expected, observed/expected ratio (o/e) 0.78, 90% interval 0.58 to 1.04. The upper end of that interval is the gene's LOEUF score, 1.04, which puts it in group 4 of 6, group 1 being the genes least tolerant of losing a copy. Missense variants: 788 observed, 871.65 expected, observed/expected ratio (o/e) 0.9, 90% interval 0.85 to 0.96. Synonymous variants: 377 observed, 351.66 expected, observed/expected ratio (o/e) 1.07, 90% interval 0.99 to 1.17.
Homologues: Orthologues: chimpanzee TTLL11 (99% identical), macaque TTLL11 (97% identical), pig TTLL11 (85% identical), guinea pig TTLL11 (81% identical), dog TTLL11 (80% identical), rabbit TTLL11 (80% identical), mouse Ttll11 (77% identical), rat Ttll11 (77% identical), tropical clawed frog ttll11 (62% identical), zebrafish ttll11 (57% identical), Caenorhabditis elegans ttll-11 (30% identical). Paralogues in human: TTLL13 (24% identical), TTLL6 (23% identical), TTLL7 (23% identical), TTLL4 (21% identical), TTLL2 (16% identical), TTLL1 (15% identical), TTLL9 (14% identical), TTLL10 (14% identical), TTLL3 (13% identical), TTLL12 (12% identical), TTLL8 (11% identical), KPRP (9% identical).
Diseases named in the same sentence as TTLL11 in open-access papers:
TTLL11 is named in the same sentence as 6 diseases in open-access papers, as found by Europe PMC text mining. Sharing a sentence is not in itself a finding about the gene and the disease. The quoted sentences say what the papers report.
scoliosis (2 papers, 2021 to 2023). A congenital or acquired spinal deformity characterized by lateral curvature of the spine. "Similarly, variants in the TTLL11 gene were present in the majority of UK families with concomitant scoliosis; a zebrafish model with the gene knocked out replicated this condition." (PMID 38322243, 2023).
cancer (2 papers, 2022 to 2025). A tumor composed of atypical neoplastic, often pleomorphic cells that invade other tissues. "In fact, we found that the rate of mutations in the coding and the untranslated region of the TTLL11 gene in cancer cells is significantly lower than expected." (PMID 36414642, 2022). "Although we could not identify a specific transcription factor that may be directly responsible for the downregulation of TTLL11 in cancer we found that there is a causal link between the increased expression of two oncogenes, CCNE1 and cdc25a, and the downregulation of TTLL11." (PMID 36414642, 2022). "The downregulation of TTLL11 was especially significant, since a recent report demonstrated that TTLL11 regulates microtubule dynamics and is frequently altered in cancer." (PMID 40083939, 2025). "Our data reveal a mechanism to ensure genome stability in normal cells that is compromised in cancer cells that systematically downregulate TTLL11." (PMID 36414642, 2022). "These two potential TTLL11 upstream regulators are actually often co-expressed in most types of cancers." (PMID 36414642, 2022). "The systematic downregulation of TTLL11 in cancer cells underscore the functional relevance of MT polyglutamylation in the spindle." (PMID 36414642, 2022). "TTLL11 downregulation in human cancer should translate into reduced levels of spindle MT polyglutamylation in cancer cells." (PMID 36414642, 2022). "Altogether, these data suggest that the downregulation of TTLL11 in human cancer is highly specific and therefore relevant functionally." (PMID 36414642, 2022). "The relevance of TTLL11 downregulation in cancer is underscored by our findings revealing that it is the only TTLL glutamylase expressed in all tissues with a tumor-specific co-expression signature." (PMID 36414642, 2022). "Stratifying patients according to the combined expression of CCNE1 and CDC25A revealed the expected pattern across most types of cancer: TTLL11 is downregulated in tumors with high expression of at least one of the two potential TTLL11 upstream regulators." (PMID 36414642, 2022). "Altogether, these data show that the systematic downregulation of TTLL11 in human cancers correlates with the reduction of polyglutamylation of the spindle MTs that may play a role in favouring chromosome mis-segregation, aneuploidy, and CIN in tumor cells." (PMID 36414642, 2022). "Altogether, these data corroborate the significance of TTLL11 downregulation in cancer." (PMID 36414642, 2022). "However, as TTLL13 basal expression levels are either low or undetectable in normal tissues, its overexpression in human cancer results in TTLL13 expression levels that are well below those of downregulated TTLL11." (PMID 36414642, 2022). "Since our results showed that TTLL11 downregulation generates aneuploidy in the daughter cells (as detected by chromosome segregation defects, including lagging chromosomes and micronuclei), we decided to explore whether TTLL11 activity is compromised in cancer cells." (PMID 36414642, 2022). "Interestingly, our data showing that the downregulation of TTLL11 result in a partial stabilization of the spindle MTs is consistent with the observation that cancer cells with CIN have hyperstable kinetochore–MT attachments as compared to stable diploid cells." (PMID 36414642, 2022). "The authors show that polyglutamylation of spindle microtubules is essential for error-free chromosome segregation and is mediated through Tubulin Tyrosine Ligase Like 11 (TTLL11), which is found to be frequently downregulated in cancer." (PMID 36414642, 2022).
tumor (1 paper, 2022). "The resulting genome-wide co-expression profiles spotlighted TTLL11 as the TTLL glutamylase with the strongest tumor-specific co-expression signature that deviates from the expression pattern found in the corresponding normal tissues." (PMID 36414642, 2022). "Altogether, our analysis suggests that the consistent downregulation of TTLL11 across tumors may be explained by the overexpression of CCNE1 or CDC25A as part of a tumor-specific transcriptional program." (PMID 36414642, 2022). "Alternatively, we hypothesized that the mRNA levels of TTLL11 may be regulated as part of a tumor-specific transcription program." (PMID 36414642, 2022).
TTLL11 also shares sentences with these, for which no sentence is quoted: hereditary spastic paraplegia (1 paper); idiopathic scoliosis (1); periodontitis (1).